PDE2A (phosphodiesterase 2A)
Diseases named in the same sentence as PDE2A in open-access papers (continued):
Sharing a sentence is not in itself a finding about the gene and the disease.
PDE2A also shares sentences with these, for which no sentence is quoted: movement disorder (5 papers); breast carcinoma (3); psychiatric disease (3); autism (2); bipolar disorder (2); depression (2); developmental delay (2); gastric tumors (2); lymphoid neoplasm (2); pulmonary hypertension (2); acute myeloid leukemia (1); adrenocortical carcinoma (1); angiomyolipoma (1); Anxiety (1); Arrhythmia (1); atypical Rett syndrome (1); bladder cancer (1); cervical squamous cell carcinoma (1); clear cell renal cell carcinoma (1); cognitive disorder (1); colon cancer (1); dysautonomia (1); Dyskinesia (1); Dystonia (1); Encephalopathy (1); endocervical adenocarcinoma (1); fragile X syndrome (1); head and neck squamous cell carcinoma (1); hemorrhage (1); Huntington disease (1).
A further 21 diseases each share a sentence with PDE2A in 1 paper.